RFX6 (regulatory factor X6)
Description:
Transcription factor required to direct islet cell differentiation during endocrine pancreas development. Specifically required for the differentiation of 4 of the 5 islet cell types and for the production of insulin. Not required for pancreatic PP (polypeptide-producing) cells differentiation. Acts downstream of NEUROG3 and regulates the transcription factors involved in beta-cell maturation and function, thereby restricting the expression of the beta-cell differentiation and specification genes, and thus the beta-cell fate choice. Activates transcription by forming a heterodimer with RFX3 and binding to the X-box in the promoter of target genes. Involved in glucose-stimulated insulin secretion by promoting insulin and L-type calcium channel gene transcription.
Synonyms: RFXDC1; MGC33442; dJ955L16.1; MTCHRS; MTFS
Tractability: No criterion of Open Targets' tractability assessment is met for any kind of drug.
Gene: Protein-coding gene on chromosome 6 (116,877,212 to 116,932,161, forward strand). Ensembl gene ENSG00000185002.
Subcellular location: Nucleus
Pathways (Reactome):
Developmental Biology: Regulation of gene expression in beta cells
Gene Ontology:
Molecular function: DNA-binding transcription activator activity, RNA polymerase II-specific; protein binding; RNA polymerase II transcription regulatory region sequence-specific DNA binding; transcription cis-regulatory region binding; DNA-binding transcription factor activity, RNA polymerase II-specific; RNA polymerase II cis-regulatory region sequence-specific DNA binding; DNA binding; DNA-binding transcription factor activity
Biological process: endocrine pancreas development; glucose homeostasis; positive regulation of DNA-templated transcription; positive regulation of insulin secretion involved in cellular response to glucose stimulus; positive regulation of transcription by RNA polymerase II; regulation of insulin secretion; pancreatic A cell differentiation; pancreatic D cell differentiation; pancreatic epsilon cell differentiation; regulation of transcription by RNA polymerase II; type B pancreatic cell differentiation; regulation of DNA-templated transcription
Cellular component: nucleus; chromatin
Genetic constraint (gnomAD): Loss-of-function variants: 32 observed, 62.08 expected, observed/expected ratio (o/e) 0.52, 90% interval 0.39 to 0.69. The upper end of that interval is the gene's LOEUF score, 0.69, which puts it in group 2 of 6, group 1 being the genes least tolerant of losing a copy. Missense variants: 731 observed, 802.03 expected, observed/expected ratio (o/e) 0.91, 90% interval 0.86 to 0.97. Synonymous variants: 268 observed, 303.16 expected, observed/expected ratio (o/e) 0.88, 90% interval 0.8 to 0.98.
Gene-disease validity (ClinGen):
ClinGen rates the evidence that RFX6 causes each of these diseases.
monogenic diabetes (autosomal dominant): Definitive. Diabetes mellitus that is caused by mutations in a single gene.
Homologues: Orthologues: chimpanzee RFX6 (99% identical), macaque RFX6 (98% identical), pig RFX6 (93% identical), rabbit RFX6 (91% identical), dog RFX6 (91% identical), mouse Rfx6 (87% identical), rat Rfx6 (86% identical), guinea pig RFX6 (80% identical), tropical clawed frog RFX6 (67% identical), zebrafish rfx6 (62% identical), Caenorhabditis elegans daf-19 (18% identical). Paralogues in human: RFX4 (30% identical), RFX1 (22% identical), RFX3 (21% identical), RFX2 (20% identical), RFX7 (15% identical), RFX8 (10% identical), RFX5 (7% identical).
Diseases named in the same sentence as RFX6 in open-access papers:
RFX6 is named in the same sentence as 52 diseases in open-access papers, as found by Europe PMC text mining. Sharing a sentence is not in itself a finding about the gene and the disease. The quoted sentences say what the papers report.
diabetes (27 papers, 2014 to 2026). "Recent studies have highlighted the pivotal role of RFX6 in human pancreatic islet development and function, and its association with diabetes." (PMID 39080045, 2024). "Mutations in RFX6 have led to different types of diabetes, raising questions about its importance in pancreatic islet development and function." (PMID 39080045, 2024). "Mice with loss of Rfx6 exhibited similarities to the human phenotype, presenting with neonatal diabetes and intestinal obstruction, albeit with variable pancreatic hypoplasia." (PMID 38743124, 2024). "In our study, the RFX6 variant was confirmed in the patient and her mother, who had diabetes since the age of 31 years." (PMID 38162681, 2023). "For example, Mitchell‐Riley syndrome caused by biallelic RFX6 pathogenic variants is characterized by neonatal/early‐onset diabetes, pancreatic hypoplasia, intestinal atresia, and gallbladder aplasia or hypoplasia." (PMID 36398453, 2023). "Notable downregulated TFs include HNF1A/B and RFX6, which have known diabetes association and/or play important roles in β-cell function." (PMID 37669939, 2023). "It has been recently proposed to focus on the enteroendocrine cell dysfunction and to use GLP-1 analogs for the management of protracted diarrhea and diabetes in patients with heterozygous RFX6 mutations." (PMID 35813646, 2022). "RFX6 heterozygotes have reduced penetrance of diabetes compared to common HNF1A and HNF4A-MODY mutations (27, 70 and 55% at 25 years of age, respectively)." (PMID 29026101, 2017). "The analysis showed that the RFX6 variant p.Leu292Ter co-segregated in 9 out of 10 individuals with diabetes (LOD score = 0.65, P = 0.04)." (PMID 29026101, 2017). "The present report reinforces that severe neonatal diabetes associated with RFX6 gene mutation constitutes a distinct phenotype presently described as Mitchell-Riley syndrome." (PMID 26770845, 2015). "Here, we show that Rfx6, whose mutation leads to neonatal diabetes in humans, is essential to maintain key features of functionally mature β cells in mice." (PMID 25497096, 2014). "While another regulatory factor X family member, RFX6, is known to regulate human islet development and mutations cause monogenic diabetes, the role of RFX3 in human development remains unclear." (PMID 40263183, 2025). "Thus, our study highlights the complexity of RFX6’s role in pancreatic islet development and its implications for understanding pancreatic hypoplasia and diabetes risk." (PMID 39080045, 2024). "The precise mechanism of how heterozygous pathogenic RFX6 variant carriers are predisposed to develop diabetes remains unknown." (PMID 38743124, 2024). "Mutations in RFX6 are involved in endocrine and exocrine pancreatic insufficiency and also in the altered maturation of the enteroendocrine cell subpopulation in the gastrointestinal tract, leading to diabetes and severe malabsorption." (PMID 34715892, 2021). "However, the genetic mutation in (regulatory factor X on chromosome 6) RFX6 was only detected in babies who had diabetes, making it different from the previously known mutations for the disease." (PMID 26761945, 2016). "It is possible that escape from NMD could lead to some retention of function of the RFX6 protein generated from that allele, with a resulting milder phenotype with respect to age of onset of diabetes and other clinical features." (PMID 26264437, 2015). "In addition to NKX6–1 we found variants in WFS1, RFX6 and 7 other genes associated with monogenic forms of diabetes (AKT2, EIF2AK3, GLIS3, HADH, MNX1, NKX2–2, and PTF1A) and they may be relevant to development of MODY." (PMID 29439679, 2018). "In this article, we review the literature surrounding RFX6 with respect to its role in development and diabetes pathogenesis." (PMID 41716817, 2026).
diabetes (continued). "While RFX6 mutations are linked to neonatal diabetes and type 2 diabetes, the role of RFX3 in diabetes is less understood." (PMID 40263183, 2025). "Human pluripotent stem cells have been extensively used to model monogenic diabetes genes, including RFX6, as they can be differentiated into stem-cell-derived islets (SC-islets) that closely mimic native human islets developmentally and functionally." (PMID 38743124, 2024). "In 2 subjects, 1 with isolated diabetes, NGS revealed heterozygous variants in 2 recessive genes known to cause syndromic PNDM (RFX6, ONECUT1)." (PMID 38408297, 2024). "While previous research shows RFX6 is crucial for islet development and glucose regulation, its exact involvement in diabetes is unclear." (PMID 39080045, 2024). "The “monogenic diabetes” gene group contains HNF1A, GCK, RFX6, and ABCC8, which harbor variants that cause MODY." (PMID 37292813, 2023). "Further studies are needed to understand the mechanism of reduced penetrance of diabetes in RFX6 heterozygotes." (PMID 29026101, 2017). "In two previously reported families of neonatal diabetes children with homozygous p.Arg181Gln RFX615, 18 or RFX6 p.His293Leufs19, the genetic information available on RFX6 heterozygous family members was also suggestive of reduced penetrance of diabetes." (PMID 29026101, 2017). "Like GCK and RFX6, homozygous variants of MNX1 could contribute to neonatal diabetes development, while heterozygous ones to rare cases of MODY." (PMID 39201476, 2024). "Moreover, differently from other forms of diabetes comprising T2DM, T1DM, and HNF1A-MODY, RFX6-MODY was associated with a decreased glucose-dependent insulinotropic peptide (GIP) secretion." (PMID 39201476, 2024). "In mice with Rfx6 gene deficiency, all endocrine cells are absent, except for polypeptide-secreting cells, resulting in diabetes and early postnatal death, limiting the exploration of its role in beta cell function and INS production." (PMID 39080045, 2024). "We demonstrate that RFX6 haploinsufficiency does not affect beta cell number or insulin content but does impair function, predisposing carriers to diabetes." (PMID 38743124, 2024). "Despite RFX6’s known function in islet development, its specific role in diabetes pathogenesis remains unclear." (PMID 39080045, 2024). "There is no known family history of diabetes; both non‐diabetic parents are heterozygous for one of the RFX6 variants." (PMID 36398453, 2023). "We assessed the diabetes phenotype in 27 RFX6 heterozygote individuals with diabetes." (PMID 29026101, 2017). "All patients had isolated diabetes and there were no reports of the other features of homozygous RFX6 mutations, such as duodenal or gall bladder atresia." (PMID 29026101, 2017). "Taking these data together, there is no support for the idea that being heterozygous for either RFX6 mutation is a risk factor for abnormal HbA1c or C-peptide levels, or diabetes." (PMID 26264437, 2015). "Genetic testing for RFX6 mutations should be considered in patients presenting with intestinal atresias in the absence of neonatal diabetes, especially where sibling recurrence or parental consanguinity point to possible autosomal recessive inheritance." (PMID 26264437, 2015). "In summary, we report two individuals each with compound heterozygous RFX6 nonsense mutations and an intestinal phenotype consistent with Mitchell–Riley syndrome, but with onset of diabetes in childhood rather than in the first 2 weeks of life." (PMID 26264437, 2015). "Genetic testing for RFX6 mutations should be considered in patients presenting with intestinal atresias in the absence of neonatal diabetes." (PMID 26264437, 2015). "Given the central position of RFX6 in pancreatic development and diabetes, understanding in more detail the regulatory role of RFX6 in different cell types and at different stages of development may open avenues towards patient-specific diabetes treatment and prevention." (PMID 41716817, 2026).
diabetes (continued). "We demonstrate that RFX6 haploinsufficiency does not affect beta cell number or insulin content but does impair function, predisposing heterozygous carriers of loss-of-function variants to diabetes." (PMID 38743124, 2024). "The later onset of diabetes in these patients may be due to incomplete inactivation of RFX6." (PMID 26264437, 2015). "Most types of monogenic diabetes have reduced penetrance and variable expressivity, including HNF1A, HNF4A, and RFX6, which is considered a candidate gene for MODY, emphasizing the role of environment and genetic factors." (PMID 40148250, 2025). "In the last decade, there are other studies that reported genes other than known OMIM MODY genes to be involved in early onset of diabetes and MODY i.e. RFX6 and WFS1 genes." (PMID 34763692, 2021). "Similar to HNF1A/HNF4A-MODY6, 38, RFX6-MODY patients lack islet autoantibodies and have isolated diabetes." (PMID 29026101, 2017). "This is a similar pattern to RFX6, an established low-penetrance cause of MODY, which had adult individuals without diabetes within the reported pedigrees." (PMID 40779032, 2025). "To remove potential confounding factors, we compared the OGTT data for the 11 Finnish RFX6 p.His293Leufs heterozygotes without diabetes to five matched (age, sex and BMI) controls for each heterozygote from the PPP-Botnia Study." (PMID 29026101, 2017). "There were 18 RFX6 heterozygotes of whom five had not developed diabetes at study entry." (PMID 29026101, 2017). "This suggests that persistent C-peptide, lack of islet autoantibodies and parental history of diabetes, which are currently used to distinguish common forms of MODY from type 1 diabetes, can also be used to identify RFX6-MODY." (PMID 29026101, 2017).
MODY (19 papers, 2017 to 2026). "Homozygous mutations in RFX6 lead to neonatal diabetes accompanied by a hypoplastic pancreas, whereas heterozygous mutations cause MODY." (PMID 39080045, 2024). "Currently, 13 genes on different chromosomes have been designated as MODY-causing genes, although mutations in other genes, such as RFX6 and APPL1, have also been reported to be associated with MODY." (PMID 37711893, 2023). "We also identified an individuals with an RFX6 protein-truncating variant previously associated with MODY with reduced penetrance." (PMID 36418577, 2023). "We focused our investigations on 14 previously identified genes ascribed to the cause of MODY and two potentially novel MODY-causing genes, RFX6 and NKX6-1." (PMID 36613572, 2022). "Twenty-three mutations were in MODY-causing genes, while five mutations were detected in potentially novel MODY-causing genes—three variants in RFX6 and two variants in NKX6-1 in seven subjects." (PMID 36613572, 2022). "Previously, however, only homozygous mutations in RFX6 had been implicated in neonatal diabetes with gut and gallbladder anomalies and the role as a MODY-gene was questionable due to variable penetrance." (PMID 30377832, 2018). "Protein truncating variants in the beta-cell transcription factor RFX6 have now been reported to cause MODY with low penetrance." (PMID 30377832, 2018). "Our study demonstrates that heterozygous RFX6 protein truncating variants are associated with MODY with reduced penetrance." (PMID 29026101, 2017). "In addition, new genes have been associated with a clinical phenotype of MODY with low penetrance, such as RFX6 (tested in our panel), a transcription factor involved in the maturation and function of the β-cell, and NKX6-1, also involved in the development of β-cells." (PMID 35769090, 2022). "In addition to known MODY genes, we report the identification of variants in RFX6, WFS1, AKT2, NKX6–1 that may contribute to development of MODY." (PMID 29439679, 2018). "Heterozygous mutations of RFX6 and RFX6 TPV, instead, have been linked to isolated MODY with reduced penetrance." (PMID 39201476, 2024). "In fact, patients with RFX6-MODY had normal development of the β islet cells but defective insulin secretion, leading to hyperglycemia." (PMID 38162681, 2023). "One individual had a protein-truncating variant in the regulatory factor X6 gene (RFX6), recently shown to be associated with MODY with reduced penetrance." (PMID 36418577, 2023). "Pregnancy management in patients with RFX6-MODY is similar to type 2 DM, although higher insulin doses may be required." (PMID 41636221, 2026). "Tirzepatide may be a beneficial therapeutic option for managing patients with RFX6-MODY who have adequate β-cell function." (PMID 41636221, 2026). "Consequently, recent studies identified RFX6 as a novel MODY gene and WFS1, PPARG, and GLIS3 have recently been proposed as potential candidates for these rare MODY forms." (PMID 34079523, 2021). "We therefore assessed their existing genetic evidence and performed the gene-level burden tests in a large MODY cohort, alongside two established MODY genes as positive controls (HNF1A-high penetrance, RFX6 -low penetrance)." (PMID 40779032, 2025). "Five out of eleven MODY genes were found affected, and these were GCK, HNF1B, HNF4A, PDX1, and RFX6." (PMID 39364395, 2024). "GCK-MODY was most common, followed by HNF4A and the lower-penetrance RFX6-MODY." (PMID 41288518, 2026). "In all cases, we observed consistent results that APPL1 and WFS1 variants are not enriched in the MODY cohort, whereas NEUROD1 and PDX1 were at a level similar to RFX6." (PMID 40779032, 2025). "Next 357 selected patients, in whom no damaging variants were found in 12 major genes causing MODY, were screened for the presence of pathogenic variants in four candidate genes (MNX1, RFX6, NKX2.2, and NKX6.1)." (PMID 34019234, 2021). "Many patients with RFX6-MODY do not appear to require insulin at diagnosis." (PMID 41636221, 2026).
MODY (continued). "Although the variants in NKX2–2, RFX6 and MNX1 have been found in recessively inherited neonatal diabetes, variants in NKX6–1 have not thus far been found in neonatal diabetes or MODY." (PMID 29439679, 2018).